TAS2R60 (taste 2 receptor member 60)
Description:
Receptor that may play a role in the perception of bitterness and is gustducin-linked. May play a role in sensing the chemical composition of the gastrointestinal content. The activity of this receptor may stimulate alpha gustducin, mediate PLC-beta-2 activation and lead to the gating of TRPM5 (By similarity).
Synonyms: T2R60; T2R56
Tractability: Antibody: its Gene Ontology location is reachable by antibodies, with high confidence; UniProt predicts a signal peptide or a membrane-spanning region. PROTAC: a small molecule that binds it is known.
Target class: Membrane receptor; Taste receptor (taste family GPCR); Taste family G protein-coupled receptor
Gene: Protein-coding gene on chromosome 7 (143,443,453 to 143,444,409, forward strand). Ensembl gene ENSG00000185899.
Subcellular location: Membrane
Pathways (Reactome):
Signal Transduction: Class C/3 (Metabotropic glutamate/pheromone receptors); G alpha (i) signalling events
Gene Ontology:
Molecular function: bitter taste receptor activity; G protein-coupled receptor activity
Biological process: detection of chemical stimulus involved in sensory perception of bitter taste; sensory perception of bitter taste; G protein-coupled receptor signaling pathway; sensory perception of taste
Cellular component: membrane; plasma membrane
Genetic constraint (gnomAD): Loss-of-function variants: 16 observed, 21.09 expected, observed/expected ratio (o/e) 0.76, 90% interval 0.51 to 1.15. The upper end of that interval is the gene's LOEUF score, 1.15, which puts it in group 5 of 6, group 1 being the genes least tolerant of losing a copy. Missense variants: 362 observed, 400 expected, observed/expected ratio (o/e) 0.9, 90% interval 0.83 to 0.99. Synonymous variants: 141 observed, 151.28 expected, observed/expected ratio (o/e) 0.93, 90% interval 0.81 to 1.07.
Homologues: Orthologues: chimpanzee TAS2R60 (97% identical), macaque TAS2R60 (90% identical), pig TAS2R60 (65% identical), rabbit TAS2R60 (64% identical), mouse Tas2r135 (57% identical), rat Tas2r135 (56% identical), guinea pig TAS2R60 (56% identical), tropical clawed frog tas2r7 (24% identical), tropical clawed frog t2r2 (24% identical), tropical clawed frog t2r10 (23% identical), tropical clawed frog t2r13 (21% identical), tropical clawed frog t2r15 (21% identical), and 9 more. Paralogues in human: TAS2R41 (38% identical), TAS2R16 (28% identical), TAS2R39 (28% identical), TAS2R40 (28% identical), TAS2R9 (27% identical), TAS2R7 (26% identical), TAS2R1 (26% identical), TAS2R8 (24% identical), TAS2R13 (24% identical), TAS2R3 (24% identical), TAS2R30 (24% identical), TAS2R46 (23% identical), and 11 more.
Diseases named in the same sentence as TAS2R60 in open-access papers:
TAS2R60 is named in the same sentence as 6 diseases in open-access papers, as found by Europe PMC text mining. Sharing a sentence is not in itself a finding about the gene and the disease. The quoted sentences say what the papers report.
Alzheimer disease (1 paper, 2024). A progressive, neurodegenerative disease characterized by loss of function and death of nerve cells in several areas of the brain leading to loss of cognitive function such as memory and language. "The identification of significant SNP-Gene associations across all 28 taste genes, particularly those leading to the down-regulation of TAS2R41 and TAS2R60, presents a notable link to Alzheimer's disease within the African American cohort studied." (PMID 39284855, 2024). "In both cases, the specific mechanisms by which TAS2R41 and TAS2R60 influence the expression or function of EPHB6 and ADGRB3 in the context of Alzheimer's disease remain to be fully elucidated." (PMID 39284855, 2024).
colon cancer (1 paper, 2024). "Differential expression analysis results revealed that compared to normal colon tissue, colon cancer samples exhibited elevated expression levels of TAS2R1, TAS2R4, TAS2R5, TAS2R14, TAS2R19, TAS2R20, and TAS2R38 (p < 0.05), with the exception of TAS2R60, which was downregulated." (PMID 38999959, 2024).
lung squamous cell carcinomas (1 paper, 2022). "TAS1R2 was mutated in roughly 5% of lung, colon, and stomach adenocarcinomas and TAS2R60 was mutated in ~ 4% of lung squamous cell carcinomas." (PMID 35624283, 2022).
TAS2R60 also shares sentences with these, for which no sentence is quoted: cancer (1 paper); skin melanoma (1); stomach adenocarcinomas (1).